PALB2 (partner and localizer of BRCA2)
Diseases named in the same sentence as PALB2 in open-access papers (continued):
Sharing a sentence is not in itself a finding about the gene and the disease.
breast cancer (continued). "The PALB2 mutation prevalence was 3.2 % (3/95) in cases with family history of breast cancer." (PMID 26489409, 2015). "The frequency of PALB2 truncating variants in this cohort (1.1 %) is similar to other studies analysing high-risk breast cancer individuals (0.64–3.4 %, 1.35 % overall) or triple-negative breast cancer (0.9–2.5 %) but is the largest to include an analysis of the full gene in both cases and controls." (PMID 26283626, 2015). "PALB2 mutations have also been observed in 1% of Chinese women with early onset breast cancer." (PMID 25869442, 2015). "Among the triple-negative breast cancers, 22 were selected cases with a family history or bilateral breast cancers, the PALB2 mutation prevalence was 9.1 % (2/22), for 2 of four patients with deleterious mutations had triple-negative breast cancer, and had family history or bilateral breast cancer." (PMID 26489409, 2015). "Looking at the family histories of these cases, 4/8 families had a history of breast cancer, suggesting that like BRCA2, mono-allelic mutations in PALB2 may lead to the development of breast cancer." (PMID 24949998, 2014). "However, pedigree inspection revealed that family F1573 was related to one of three PALB2 p.Q775X (P28031) families described in the initial report of this variant in the French Canadian breast cancer families." (PMID 23302520, 2013). "Thus, tumors of the 1592delT PALB2 mutation carriers presented triple negative phenotype more often (54.5%, P<0.0001) than those of other familial (12.2%) or sporadic (9.4%) breast cancer patients." (PMID 23935836, 2013). "Moreover, the overrepresentation of mutations in the cohort of women with contralateral breast cancer is important to the clinical management of women carrying PALB2 mutation as it implies a significant risk of developing a second primary breast neoplasm." (PMID 23586058, 2013). "Thus, PALB2 monoallelic mutations have been identified in approximately 1% of hereditary breast cancer families globally, as summarized by Tischkowitz and Xia." (PMID 23935836, 2013). "Individuals who carry germline mutations in the PALB2 gene are at increased risk of breast cancer." (PMID 23941127, 2013). "Thus, this relatively common mutation in PALB2 is associated with a high risk of developing breast cancer." (PMID 23941127, 2013). "Rahman et al63 reported truncating PALB2 mutations in 10/923 individuals with familial breast cancer and no such mutations in healthy controls, suggesting that such mutations conferred a relative risk of 2.3 for breast cancer." (PMID 23318652, 2013). "Heterozygosity for PALB2 c.1592delT has a strong effect on breast cancer risk." (PMID 23941127, 2013). "In multiple-breast cancer case families, germline PALB2 mutations have been reported in 1.1% (10 out of 920), 2.7% (3 out of 113), 2.0% (1 out of 50), and 0.6% (5 out of 779) of Western European families in the United Kingdom, Finland, French-Canada, and Australasian, respectively." (PMID 23977390, 2013). "PALB2 mutations have been associated with breast cancer in several studies." (PMID 23110154, 2012). "Another example is the Finnish founder PALB2 mutation; on the basis of studying cases unselected for family history, it has been estimated to be associated with a sixfold increased risk and a cumulative breast cancer risk of 40% by age 70 years." (PMID 21182766, 2010). "The c.509_510delGA is a novel PALB2 mutation that increases the risk of familial breast cancer." (PMID 20122277, 2010). "In addition, PALB2 has recently been identified as a breast cancer susceptibility gene in several populations." (PMID 18501021, 2008). "In addition, PALB2 has recently been identified as a breast cancer susceptibility gene in several populations, but its association with increased risk for ovarian cancer has not been established." (PMID 18501021, 2008).
breast cancer (continued). "The OR for breast cancer in association with a truncating PALB2 mutation cannot easily be determined as the numbers of mutation carriers in each study are small, but the two studies in which it has been calculated (using very different methods) found ORs of 2.3 and 3.9, respectively." (PMID 18053174, 2007). "Deleterious PALB2 alleles are extremely rare in the general population, and only in Finland have any variants been found in individuals outside the setting of familial breast cancer." (PMID 18053174, 2007). "PALB2 has recently been identified as a breast cancer susceptibility gene." (PMID 18053174, 2007). "PALB2 mutations are rare causes of hereditary breast cancer but may be important in countries such as Finland where a founder mutation is present." (PMID 18053174, 2007). "Overall, it appears that PALB2 mutations are responsible for 1% to 2% of strongly familial breast cancer, but in Finland (and possibly in other founder populations), PALB2 mutations may account for up to 1% of all breast cancer." (PMID 18053174, 2007). "L35P is a VUS in PALB2 that may be associated with an increased risk of breast cancer." (PMID 39745016, 2025). "Notably, a frameshift deletion in the partner and localizer of BRCA2 (PALB2), a well-established breast cancer susceptibility gene involved in HR-mediated DSBs repair, was found in a family with a history of both gastric and breast cancers, suggesting PALB2 as a novel contributor to HDGC risk." (PMID 40869030, 2025). "Clinically, these pathways could represent actionable vulnerabilities; targeting IQGAP1 or its interaction networks might offer novel therapeutic strategies for PALB2-mutated breast cancers, particularly those resistant to conventional DNA repair-targeted treatments." (PMID 40868059, 2025). "The rarity of PALB2 pathogenic variants may restrict the statistical power of our analysis, and larger scale cohorts of early-onset breast cancer require further assessment to determine whether there is a significant association between age at early onset and PALB2 pathogenic variants." (PMID 38914840, 2024). "However, among the 10 PALB2 variants found in the Korean genomic database, c.1048C>T;p.(Gln350Ter) and c.3267_3268del;p.(Phe1090SerfsTer6) were consistent with two Korean breast cancer patients among Korean breast, ovarian, and pancreatic ductal adenocarcinoma patients." (PMID 39409938, 2024). "Given the elevated lifetime risk, many female BRCA1/2 and PALB2 germline pathogenic variant carriers (herein referred to as “carriers”) may wish to consider risk-reducing mastectomy (RRM) in order to prevent the development of breast cancer." (PMID 38248108, 2024). "Including PALB2 in the routine molecular genetic testing of breast cancer patients is recommended because it is associated with high cancer risk, and preventive and screening programs in PALB2 carriers may improve their life expectancy similarly to BRCA1/2 carriers." (PMID 37686625, 2023). "These variants with impact on PALB2 function may be related to the increased risk of breast cancer." (PMID 35853885, 2022). "Several reports also demonstrated the existence of other genes at medium and low penetrance (e.g., BRIP1, RAD51C, RAD51D, BARD1, and PALB2), which have been associated with both Breast Cancer (BC) and OC risk." (PMID 35053526, 2022). "Thus, one may wonder whether the exposome can induce C > T mutations in the breast cancer-predisposing gene PALB2." (PMID 36278678, 2022).
breast cancer (continued). "In case of tumor progress, the combination of PARP-inhibitors like Olaparib with Pembrolizumab could be a promising therapeutic approach considering the detected PALB2 mutation in this case because response to PARP inhibition has already been reported for PALB2-mutated breast cancer." (PMID 36387226, 2022). "This study identified putative pathogenic variants in ATM, BRCA1, BRCA2, CHEK2, and PALB2 as the most prominent genes for breast cancer, harboring protein-truncating variants that confer significant disease risks (odds ratio of 2.10 to 10.57) to overall breast cancer risk." (PMID 34439109, 2021). "Similarly, another PALB2 pathogenic variant, c.2323C>T was identified in French-Canadian women in Quebec, where the Q775X mutation occurred in about 0.5% of the women diagnosed for breast cancer." (PMID 34439348, 2021). "In Poland, two founder PALB2 mutations were detected (c.509_510delGA, c.172_175delTTGT) and were associated with a 4.5-fold increased risk of breast cancer in unselected Polish women similar to the odds ratio we found for young breast cancer patients (OR = 3.6; 95% CI 1.7–7.9)." (PMID 32824581, 2020). "Consequently, a large number of people have already undergone genetic testing of PALB2 to identify variants that may increase the risk of breast cancer susceptibility." (PMID 33195396, 2020). "However, when compared to our findings, we found that all the PALB2-germline mutations in our PALB2-associated breast cancers were high risk frameshift, stopgain or splicing mutations, while most of the PALB2-germline mutations in PALB2-NULL patients (7/10) were moderate missense mutation." (PMID 33193564, 2020). "First, as a result of the rarity of PALB2-associated breast cancers, the small sample size may have limited the detection of significant differences in the exploratory analyses comparing PALB2-associated breast cancers with non-BRCA1/2/PALB2-associated breast cancers from TCGA." (PMID 31428676, 2019). "CN analysis revealed that the 17 BRCA1-associated breast cancers with bi-allelic inactivation had higher frequencies of gains of 3q and 6p and losses of 17q, among other differences (P < 0.05, Fisher’s exact test), as compared to the 16 PALB2-associated breast cancers with bi-allelic inactivation." (PMID 31428676, 2019). "Here we sought to characterize the repertoire of somatic genetic alterations of breast cancers from pathogenic PALB2 germline mutation carriers using a combination of whole-exome and targeted massively parallel sequencing to define whether bi-allelic PALB2 inactivation is present in these tumors." (PMID 31428676, 2019). "Because monoallelic mutation of the PALB2 gene is associated with an approximately six-fold increased risk of breast cancer in female patients, National Comprehensive Cancer Network guidelines recommend an annual mammogram and breast magnetic resonance imaging for mutation carriers of PALB2." (PMID 30840646, 2019). "Therefore, the proportion of PALB2-associated breast cancers with HRD may be even higher than that reported here and in previous analyses." (PMID 31428676, 2019). "Interestingly, the proportion of PALB2-associated breast cancers displaying mono-allelic PALB2 inactivation was comparable to the one of BRCA1-associated and BRCA2-associated breast cancers from TCGA harboring BRCA1 or BRCA2 mono-allelic inactivation, respectively." (PMID 31428676, 2019). "Hence, PALB2 missense variants causing the loss of the binding with BRCA1 might confer different risk magnitude for breast cancer." (PMID 30410870, 2018). "In this study, we examined the exomes of key members of a multiple-case family segregating the pathogenic PALB2:c.3113G>A (p.Trp1038*) mutation (Family A) to explore the possibility that additional genetic factors could be responsible for modifying the breast cancer risk in this family." (PMID 29422015, 2018). "Therefore, germline mutations in PALB2 should be tested in Chinese at high risk for breast cancer." (PMID 23318652, 2013).
breast cancer (continued). "The low frequency of PALB2 mutation carriers identified thus far may argue a minor role for this gene in conferring ovarian cancer risk compared with higher frequency of mutation carriers observed in breast cancer cases and breast cancer families." (PMID 23302520, 2013). "We tested for PALB2 mutations using HRM curve analysis to scan DNA extracted from peripheral blood samples taken from a sample unselected for family history of women diagnosed with breast cancer before the age of 40 years (probands) from a population-based case control family study (ABCFR)." (PMID 21182766, 2010). "Although predisposing PALB2 mutations generally appear to cause moderate risk of breast cancer, mutations have also been found in strong hereditary breast cancer families and might thus be worthwhile searching for by linkage analysis in e.g. geographically confined populations." (PMID 18637200, 2008). "We performed PALB2 mutation analysis in a series of unrelated French-Canadian women with breast cancer diagnosed at a single hospital in Montreal, Quebec, with the aim of identifying possible founder mutations and determining their contribution to breast cancer." (PMID 18053174, 2007). "In this study, we aimed to investigate the splicing impact of +2T variants in the breast cancer susceptibility genes ATM, BRCA1, and PALB2." (PMID 41230741, 2026). "We investigated the contribution of non-coding variation to hereditary breast cancer by analyzing intronic variants and 5' upstream regions of BRCA1, BRCA2 and PALB2 in the BEACCON case-control study of over 11,000 participants." (PMID 41935071, 2026). "We characterized breast cancer risk associated with established risk factors among WHI participants who carry PVs in BRCA1/2, ATM, CHEK2, and PALB2." (PMID 40298171, 2025). "This is in parallel with variants in genes implicated in hereditary breast cancer including the ‘high risk’ genes BRCA1, BRCA2, and PALB2 and ‘moderate risk’ genes CHEK2 and ATM." (PMID 41327266, 2025). "For the BRCA1, BRCA2, PALB2, CHEK2, and ATM genes, most protein-truncating variants have been associated with a high risk of breast cancer." (PMID 39858629, 2025). "The reported family history for the identified BRCA1, BRCA2 and PALB2 carriers revealed additional breast cancer diagnoses in 1st or 2nd degree relatives for over half of the cases, whereas ovarian cancers were less frequent." (PMID 40009290, 2025). "For instance, heterozygosis in PALB2, BRIP1, and ATM increases the lifetime risk of breast cancer, while homozygosis causes multisystemic genetic syndromes, such as Fanconi’s anemia (PALB2 and BRIP1) and ataxia-telangiectasia (ATM)." (PMID 39858629, 2025). "Conversely, BRCA2, ATM, PALB2, and CHEK2 were more commonly associated with later-onset breast cancer, for which the penetrance estimates ranged from 19% to 31% by age 60 years." (PMID 39858629, 2025). "Chemotherapy receipt was 80.6% in BRCA1-associated breast cancers compared to 56.9% in BRCA2 and 84.2% in PALB2 associated breast cancers (p < 0.001)." (PMID 40275390, 2025). "PALB2 (partner and localizer of BRCA2) is another crucial gene associated with susceptibility to breast cancer, Fanconi anemia, and other cancers." (PMID 39745016, 2025).
breast cancer (continued). "The results showed an association between the 86-SNV PRS and breast cancer risk for each of the carrier populations: BRCA1 (OR 1.20; 95% CI 1.10–1.32), BRCA2 (OR 1.23; 95% CI 1.12–1.34), ATM (OR 1.37; 95% CI 1.21–1.55), and PALB2 (OR 1.34; 95% CI 1.16–1.55)." (PMID 39858629, 2025). "Protein-truncating variants in established susceptibility genes BRCA2, BRCA1, CHEK2, PALB2, ATM and MAP3K1 were associated with a risk of breast cancer, while BARD1 and ATRIP met exome-wide significance for the first time." (PMID 41044259, 2025). "In most breast cancer susceptibility genes, Polish common founder mutations are present, including BRCA1, BRCA2, PALB2, and CHEK2, which constitute the majority (>80%) of all mutations detected in these genes in Polish women with breast cancer." (PMID 40649769, 2025). "Twenty-four individuals (16.8% [95% CI, 11.1%-23.9%]) with germline testing had PGVs in breast cancer susceptibility genes, including BRCA1 (n = 17 [70.8%]), BRCA2 (n = 5 [20.8%]), PALB2 (n = 1 [4.2%]), and CHEK2 (n = 1 [4.2%])." (PMID 39964682, 2025). "For PALB2 carriers, breast cancers are felt to be biologically similar to BRCA2 cases, however there remains a paucity of data on breast cancer treatment and outcomes." (PMID 40275390, 2025). "We report on penetrance and breast cancer risk–modifying factors for PVs in BRCA1/2, ATM, CHEK2, and PALB2 among WHI participants." (PMID 40298171, 2025). "In comparison, 76% of BRCA2/PALB2 carriers with T1N0 breast cancer had ER + HER2- disease, only half of whom received chemotherapy (eTable 1)." (PMID 40275390, 2025). "A strong association between the risk of breast cancer and family history was found for ATM, BRCA1, BRCA2, CHEK2, and PALB2 P/LP variant carriers." (PMID 39858629, 2025). "Eight different genes, including ATM, BRCA1, BRCA2, CHEK2, PALB2 (FANCN), RAD51C, and RAD51D, demonstrate significant correlations with an increased risk of breast cancer when harboring pathogenic variations." (PMID 40800071, 2025). "Among TNBC stage I-III (N = 321) and stage IV (N = 216) breast cancers, the most frequent alterations were mutations in PIK3CA (19.9% vs 21.3%), BRCA1/2 (11.5% vs 12.0%), ESR1 (0.31% vs 0%), PALB2 (0.9% vs 1.4%), and PD-L1 amplification (2.2% vs 4.6%)." (PMID 40421962, 2025). "Most breast cancer susceptibility genes are involved in the damage repair signaling pathway, i.e., including BRCA1, BRCA2, PALB2, CHEK2, ATM, BARD1, RAD51C, and RAD51D." (PMID 40649769, 2025). "Background/Objectives: Germline pathogenic variants (GPVs) in PALB2, RAD51C, and RAD51D increase breast cancer (BC) and ovarian cancer (OC) risk." (PMID 40428378, 2025). "Multiple other players from the DDR pathway, including PALB2, ATM, and CHEK2, are also connected to breast cancer predisposition, although with lower risk." (PMID 40009290, 2025). "A similar calculation for breast cancer was conducted by using BRCA1/2 as high-risk genes and CHEK2, ATM and PALB2 for intermediary risk genes." (PMID 40016794, 2025). "An analysis used breast cancer microsimulation models from the Cancer Intervention and Surveillance Modeling Network to compare different screening strategies for ATM, CHEK2, or PALB2 P/LP variant carriers." (PMID 39858629, 2025).